PSKH2 (protein serine kinase H2)
Tractability: Small molecule: it belongs to a druggable protein family.
Gene: Protein-coding gene on chromosome 8 (86,047,109 to 86,088,621, reverse strand). Ensembl gene ENSG00000147613.
Subcellular location (Human Protein Atlas): Nucleoplasm; Cytosol; Nuclear bodies
Gene Ontology:
Molecular function: protein binding; protein serine/threonine kinase activity; ATP binding; protein kinase activity; protein serine kinase activity
Cellular component: cytoplasm
Genetic constraint (gnomAD): Loss-of-function variants: 17 observed, 23.77 expected, observed/expected ratio (o/e) 0.72, 90% interval 0.49 to 1.07. The upper end of that interval is the gene's LOEUF score, 1.07, which puts it in group 4 of 6, group 1 being the genes least tolerant of losing a copy. Missense variants: 516 observed, 506.61 expected, observed/expected ratio (o/e) 1.02, 90% interval 0.95 to 1.1. Synonymous variants: 188 observed, 193.71 expected, observed/expected ratio (o/e) 0.97, 90% interval 0.86 to 1.1.
Homologues: Orthologues: chimpanzee PSKH2 (97% identical), macaque PSKH2 (96% identical), rabbit PSKH2 (84% identical), dog PSKH2 (82% identical), guinea pig PSKH2 (80% identical), Caenorhabditis elegans R06A10.4 (35% identical). Paralogues in human: PSKH1 (63% identical), CAMK1D (36% identical), CAMK1 (34% identical), CAMK1G (34% identical), PNCK (33% identical), DCLK1 (31% identical), DCLK2 (31% identical), CAMKV (31% identical), CAMK2D (28% identical), STK33 (28% identical), DCLK3 (27% identical), CAMK2A (26% identical), and 10 more.
Diseases named in the same sentence as PSKH2 in open-access papers:
PSKH2 is named in the same sentence as 5 diseases in open-access papers, as found by Europe PMC text mining. Sharing a sentence is not in itself a finding about the gene and the disease. The quoted sentences say what the papers report.
breast carcinoma (1 paper, 2020). "ADCK5, ETNK2, PSKH2, RPS6KC1, and SCYL3 are all significantly focally amplified in breast cancer samples as well but are not located in a peak region." (PMID 33205077, 2020).
cancer (2 papers, 2020 to 2023). A tumor composed of atypical neoplastic, often pleomorphic cells that invade other tissues. "PSKH2 is also a frequently mutated ‘dark’ pseudokinase in human cancers, with the majority of mutations mapping to specific regions in the N-terminal domain and the pseudokinase domain." (PMID 36520605, 2023). "Our work also provides an opportunity to assess the relative functional contributions of amino acid mutations in human PSKH2 that are reported to be enriched with human cancers, many of which are found in the C-lobe of the pseudokinase domain." (PMID 36520605, 2023). "For example, assessment of 24 cancer cohorts found significantly elevated copy numbers of PSKH2 genes in 5–10% of all patients which was also prognostic for poor survival in some cancers." (PMID 36520605, 2023). "Cox-proportional hazard ratios on Tdark kinases and their CNAs reveal that SBK2, ETNK2, PSKH2, SCYL3, and NRBP2 are all significantly prognostic for survival across all cancers." (PMID 33205077, 2020).
PSKH2 also shares sentences with these, for which no sentence is quoted: erythroleukemia (1 paper); neuropathy (1); preeclampsia (1).